TNF (tumor necrosis factor)
Diseases named in the same sentence as TNF in open-access papers (continued):
Sharing a sentence is not in itself a finding about the gene and the disease.
inflammatory bowel disease (continued). "In chronic inflammatory diseases (e.g., rheumatoid arthritis, inflammatory bowel disease—IBD) IFX seems to work by preventing TNF-α from binding to its receptor in the cell, which blocks further cytokine inflammatory cascade and leads to the development of disease." (PMID 34300342, 2021). "The inflammatory bowel disease index, i-NOS, NO, MDA, and COX-2 in colon tissues and TNF-α, MPO, and IL-1β in blood serums, were decreased in the treatment group as compared to the model group." (PMID 33499333, 2021). "Tumor necrosis factor alpha (TNF-α) and interleukin 6 (IL-6) play essential roles in the pathophysiology of inflammatory bowel disease." (PMID 32090060, 2020). "Anti-TNF agents are the first class that inhibit cytokine TNF-alpha, approved by FDA for the treatment of Inflammatory bowel disease." (PMID 33123434, 2020). "In colonic biopsies from patients with inflammatory bowel disease (IBD), SIRT1 was downregulated by TNF-α and IL-21 in the mucosa." (PMID 33414704, 2020). "The first case of PP induced by anti -TNF-α treatment was described in a patient affected by inflammatory bowel diseases (IBD) more than 15 years ago, and later, an increasing number of cases of PP has been reported in the literature, mainly due to the widespread use of anti-TNF-α drugs." (PMID 33114187, 2020). "Under the poor environment resulting from a series of factors, such as post SBTx surgery and inflammatory bowel disease (IBD), the level of tumor necrosis factor alpha (TNF-α) in the intestinal micro-environment increases significantly." (PMID 32587254, 2020). "Given that IL11 expression in colonic stromal cells predicts anti-TNF therapy failure in patients with ulcerative colitis or Crohn’s disease, we suggest IL11 as a therapeutic target for inflammatory bowel disease." (PMID 31917819, 2020). "Spondyloarthritis (SpA) and inflammatory bowel diseases (IBD) are chronic inflammatory diseases characterized by an aberrant immune response and inflammation with a key role for TNF in their pathogenesis." (PMID 30745872, 2019). "In an in-vitro study, a significant reduction was seen in several inflammatory biomarkers including tumor TNF-α, IL-1α, IL-6, IL-8, T-cell interferon-gamma (IFN-γ), and IL-2, in the presence of ≥10 μg/ml garlic extract in inflammatory bowel disease." (PMID 30683061, 2019). "In patients with inflammatory bowel disease (IBD) (i.e. UC or Crohn’s disease), serum TNF concentrations are significantly higher compared to healthy controls." (PMID 31489538, 2019). "Additionally, thalidomide has also been revealed to improve clinical outcomes of patients with refractory inflammatory bowel disease (IBD) through diminishing TNFα and interleukine-12 expression." (PMID 30836705, 2019). "More recently, OSM signaling was identified as a driver of inflammatory bowel disease (IBD), especially in patients who fail to respond to anti-tumor necrosis factor-α (TNF-α) antibodies." (PMID 31684144, 2019). "TNFα-blocking agents, including infliximab (IFX), have revolutionized the treatment of moderate to severe inflammatory bowel disease and have been reported to induce rapid symptom resolution and to facilitate steroid tapering even in CS-refractory irEC cases." (PMID 30305177, 2018). "In addition, direct evidence from human studies with inflammatory bowel disease (IBD) suggests that early TNF inhibition dramatically reduces the incidence of PD." (PMID 30374287, 2018). "Conversely, in inflammatory bowel disease (IBD), these transporters can be inhibited by cytokine TNF-α, and consequently butyrate uptake can be down-regulated." (PMID 29597260, 2018). "Neutrophils have been found to play an important role in the pathogenesis of inflammatory bowel disease (IBD), and anti-TNF-α mAb (i.e., infliximab) therapy is demonstrated to be effective in the induction of clinical remission and mucosal healing in these patients." (PMID 30595666, 2018).
inflammatory bowel disease (continued). "As part of the treatment strategy for patients with inflammatory bowel disease (IBD), inhibitors of tumor necrosis factor alpha (TNFα) have been shown to be effective in reducing their symptoms associated with IBD." (PMID 30460097, 2018). "In a similar fashion, also patients with Inflammatory bowel disease (IBD) had intestinal proinflammatory EVs with elevated levels of IL-6, IL-8, and TNF on mRNA as well as protein level compared to healthy controls." (PMID 28491866, 2017). "Faecal calprotectin is regularly used as indicator for the main inflammatory bowel diseases (IBD) such as Crohn’s disease and ulcerative colitis, meanwhile TNF-α and IL-6 are proinflammatory cytokines which have been linked with abdominal obesity and the metabolic syndrome." (PMID 28335517, 2017). "Proinflammatory cytokines tumor necrosis factor-α (TNF- α) and interleukin-1β (IL-1 β) are overexpressed in inflammatory bowel diseases and directly damage the intestinal barrier including the interepithelial TJs." (PMID 28103316, 2017). "Tumor Necrosis Factor inhibitors (TNFi) have revolutionized therapy for a variety of autoimmune conditions, including pediatric and adult arthritis and inflammatory bowel disease (IBD)." (PMID 29121953, 2017). "Infliximab®, one of the most efficient drugs against inflammatory bowel diseases (IBD), is a recombinant antibody targeting TNF-α, a major pro-inflammatory cytokine." (PMID 27142045, 2016). "For families of children and adolescents with juvenile idiopathic arthritis (JIA) or inflammatory bowel disease (IBD), our prior, qualitative research found that the decision to start TNF-α inhibitors can be particularly challenging due to the need to balance disease severity with side-effect risks." (PMID 27641835, 2016). "Infliximab is a mAb against TNF-α and used in the treatment of inflammatory bowel diseases (IBD)." (PMID 27706175, 2016). "The monoclonal antibodies against tumor necrosis factor (TNF) – infliximab (IFX) and adalimumab (ADA) – are increasingly used to treat inflammatory bowel disease (IBD) that is refractory to standard medication." (PMID 27123185, 2015). "Antibodies against tumor necrosis factor alpha, such as infliximab (IFX), are increasingly being used to treat inflammatory bowel disease." (PMID 26518665, 2015). "Treatment of inflammatory bowel disease (IBD) depends on long-term anti-inflammatory agents, such as 5-ASA, immunosuppressant and newly developed anti-tumor necrosis factor agents." (PMID 24618122, 2014). "CD4+ T cells play a central role in the development of inflammatory bowel disease (IBD) via high-level production of effector cytokines such as IFN-γ and TNF-α." (PMID 23840334, 2013). "We have previously shown that expression of PHB protein is reduced in mucosa during active inflammatory bowel disease and in Caco2-BBE cells treated with TNFα or exogenous oxidants." (PMID 22363587, 2012). "The production of proinflammatory cytokines, such as interleukin-6, interleukin-12, and tumor necrosis factor (TNF-α), is universally increased in patients with inflammatory bowel disease." (PMID 23056142, 2012). "The cytokines TNF (TNFSF2) and IFNγ are important mediators of inflammatory bowel diseases and contribute to enhanced intestinal epithelial permeability by stimulating apoptosis and/or disrupting tight junctions." (PMID 21853060, 2011). "What does seem likely, however, is a risk of developing hepatosplenic T cell lymphomas in children with inflammatory bowel disease (IBD) treated with a combination of azathioprine or 6-mercaptopurine (6-MP), and a monoclonal antibody (mAb) directed against TNF (e.g., infliximab or adalimumab)." (PMID 20712883, 2010). "Anti-TNF therapies are used to treat several pediatric diseases including juvenile idiopathic arthritis (JIA), inflammatory bowel disease (IBD) and psoriasis (PsO)." (PMID 20546618, 2010).
inflammatory bowel disease (continued). "In keeping with this observation, beneficial effects of anti-TNF agents have been reported in a few patients each with CRMO, SAPHO syndrome, and inflammatory bowel disease related CRMO." (PMID 19138427, 2009). "It is suggested that cytokines like TNF-α and IFN-γ that are frequently elevated in patients with inflammatory bowel disease, can promote the reactivation of a latent CMV infection." (PMID 18371229, 2008). "Also reports of this cytokine in inflammatory bowel disease IBD are somewhat contradictory, whereas some groups were able to demonstrate increased levels of TNF others were unable to detect it in patients with IBD." (PMID 17069659, 2006). "Infliximab, a monoclonal antibody targeting tumor necrosis factor alpha (TNFα), is usually considered as the preferred second-line therapy, due to its ability to induce a rapid clinical response, analogous to its established efficacy in the treatment of inflammatory bowel disease (IBD)." (PMID 41156090, 2025). "While these CP-related findings differ from intestinal CD, we could detect a higher abundance of predictive protein markers for anti-TNF-α therapy in CD esophagitis as described in serum of inflammatory bowel disease (IBD) patients such as CRP, ITGAV, APOE, and CLU (Fig. EV4C)." (PMID 39901020, 2025). "Data indicate that earlier initiation of anti-tumor necrosis factor alpha (anti-TNF-α) biologic medicines may prevent progression to irreversible bowel damage and improve outcomes for patients with inflammatory bowel disease (IBD), particularly Crohn’s disease." (PMID 40095484, 2025). "Indeed, Fc receptor–mediated effects contribute to the therapeutic response to infliximab and adalimumab in mouse models of inflammatory bowel disease (IBD), and patients with IBD only respond to full IgG1 anti-TNF therapies via macrophage IL-10 signaling." (PMID 40337865, 2025). "Although previous inflammatory bowel disease (IBD) studies have implicated activated fibroblasts, neutrophils, inflammatory monocytes and activated T and IgG+ plasma cells with anti-TNF nonresponse, no biomarker is currently approved for response prediction." (PMID 39438660, 2024). "Likewise, the pre-treatment of NaB obviously represses the expression levels of IL-6 and TNF-α in RAW246.7 macrophages induced by lipopolysaccharide in vitro, suggesting its anti-inflammatory property in inflammatory bowel disease." (PMID 38616256, 2024). "High concentrations or certain structural forms may increase cytokine production (e.g., IL-6, TNF-α) in immune cells, potentially exacerbating inflammation in conditions like inflammatory bowel disease (IBD) depending on concentration and the inflammatory environment." (PMID 39598865, 2024). "Lastly, anti-TNF inhibitors, such as infliximab, have been administered to patients with MIS-C, as they are widely used for the treatment of rheumatoid arthritis, ankylosing spondylitis, inflammatory bowel disease (IBD), and refractory Kawasaki disease." (PMID 39457145, 2024). "Approximately one out seven (14%) “D2T” patients had a comorbidity such as multiple sclerosis, Inflammatory bowel disease (IBD), recurrent uveitis or solid cancer within the past five years, which serves as a contraindication for the use of anti-TNF or anti-IL-17 inhibitors." (PMID 39974593, 2024). "Anti-tumour necrosis factor [anti-TNF] therapy is widely used for the treatment of inflammatory bowel disease, yet many patients are primary non-responders, failing to respond to induction therapy." (PMID 37776235, 2024). "Seven genes IL10, IL4, IL6, IFNG, IL1B, TNF and IL17A, were engaged in Inflammatory bowel disease." (PMID 36989283, 2023). "TNF-α inhibitors (TNFis) have revolutionized the treatment of certain chronic immune-mediated diseases, being widely and successfully used in rheumatic inflammatory diseases, and have also proved their efficacy in the treatment of inflammatory bowel disease (IBD)." (PMID 37629636, 2023).
inflammatory bowel disease (continued). "KEGG pathway enrichment analysis showed that these DEGs were enriched in inflammation-related pathways, including cytokine—cytokine receptor interaction, the TNF signaling pathway, the PI3K-Akt signaling pathway, inflammatory bowel disease, the NF-kappaB signaling pathway, and tight junctions." (PMID 37299390, 2023). "This may be attributed to the more common usage of infliximab since it was the first TNF-α inhibitor to receive U.S. Food and Drug Administration (FDA) approval in 1998 for inflammatory bowel disease (IBD)." (PMID 37664349, 2023). "In addition, EPS which were isolated from L. plantarum YW11 reduced the production of the proinflammatory cytokines (TNFα, IL-1β, IL-6, IFN-γ, IL-12 and IL-18) and up-regulated IL-10, and this resulted in an amelioration of inflammatory bowel disease symptoms." (PMID 36769176, 2023). "Healthy intestinal NFs activate STAT1 signaling in colon cancer cells and restrain their growth, effects not imposed by CAFs or NFs treated with TNFα or by intestinal fibroblasts from patients with inflammatory bowel disease that produce high levels of TNFα." (PMID 37046676, 2023). "In inflammatory bowel diseases, for instance, up to 40% of the patients do not respond to anti-TNFα treatments." (PMID 35890077, 2022). "Although it is useful in the treatment of inflammatory bowel disease (IBD) by inhibiting intestinal lymphocyte infiltration, it has little effect on organs other than the intestinal tract, and it is said to be safer than conventional anti-TNF-α antibody formulations." (PMID 36289788, 2022). "ANAPC11 is anaphase promoting complex subunit 11 and, to the best of our knowledge, was never before mentioned in relation to inflammatory bowel disease or anti-TNF response." (PMID 36145641, 2022). "LAYN was also involved in the epithelial-mesenchymal transition (EMT) of renal tubular epithelial cells induced by tumor necrosis factor-α (TNF-α), and played a key role in the tight junctions of the intestinal epithelium induced by HA35 in inflammatory bowel disease." (PMID 36260222, 2022). "Vedolizumab therapy is effective in both induction and maintenance of remission in inflammatory bowel disease patients who are resistant to anti-tumor necrosis factor or who can not receive anti-tumor necrosis factor therapy due to side effects." (PMID 35946879, 2022). "Rag-/-/SCID: Recombination activating genes knockout model/severe combined immunodeficiency; TNF: Tumor necrosis factor; UC: Ulcerative colitis; TLR: Toll-like receptors; Treg cells: Regulatory T cells; CD40LTG: CD40 ligand transgene; IFNγ: Interferon-gamma; IBD: Inflammatory bowel disease." (PMID 36039239, 2022). "TNF-α is not typically present in healthy humans, but increased levels are often found in inflammatory bowel diseases, where it leads to pathological inflammation." (PMID 34604282, 2021). "In addition, we obtained the following pathways: Salmonella infection, natural killer cell-mediated cytotoxicity, inflammatory bowel disease (IBD), TNF signaling pathway, and antigen processing and presentation." (PMID 33511207, 2021). "Non-responsiveness to anti-TNF-α therapies presents relevant rates in inflammatory bowel disease patients, presenting the need to find biomarkers involved in therapeutic efficacy." (PMID 34603288, 2021). "In addition to anti-cancer drugs, immune modulating agents such as tumor necrosis factor (TNF) inhibitors, used to treat inflammatory bowel disease or rheumatologic diseases, can also induce HBV reactivation." (PMID 35096867, 2021). "These upregulated DEGs were associated with KEGG pathways including the cytokine-cytokine receptor interaction, influenza A, Jak-STAT signaling, IL-17 signaling, inflammatory bowel disease (IBD), measles, NOD-like receptor signaling, TNF signaling, and NF-κB signaling pathways." (PMID 34490145, 2021).
inflammatory bowel disease (continued). "Interestingly, in a retrospective study of inflammatory bowel disease (IBD), there was a substantially reduced PD incidence among IBD patients that were exposed early to anti-TNF-α therapy." (PMID 34070609, 2021). "Considering the permissive effects of TNF and the complexity of inflammatory bowel disease, it should not be surprising that disease progression requires an interplay of the epithelial, stromal, and hematopoietic compartments." (PMID 32671059, 2020). "TNF can induce TL1A both ex vivo in fibroblast-like synoviocytes, and in mouse models of inflammatory bowel disease, raising the possibility that TL1A expression may be under the control of TNF in RA." (PMID 32381123, 2020). "Although more targeted therapies have successfully been introduced, such as anti-tumor necrosis factor (TNF) for arthritic disorders and inflammatory bowel diseases (IBD), these therapies are not without limitations." (PMID 33071974, 2020). "Furthermore, men prescribed anti-TNF agents are a unique population in that their primary disease (e.g. inflammatory bowel disease (IBD) or ankylosing spondylitis) can affect sexual function and desire, which could also impact their fertility." (PMID 32718310, 2020). "In humans, increased tumor sc-IgGs were found to be associated with poor breast cancer patient outcomes and high levels of MMP3-/MMP12-cleaved IgG were detected in sera from inflammatory bowel diseases patients, who did not respond to anti-TNFα therapy." (PMID 32117299, 2020). "Remarkably, the incidence of PD in patients with inflammatory bowel disease was reduced by almost 80% in those exposed to anti-TNF therapy compared with patients who did not receive anti-TNF agents." (PMID 32059608, 2020). "A PubMed literature search was performed and included articles published after 2000 using the following terms: child or paediatric, Crohn, ulcerative colitis, inflammatory bowel disease, anti-TNF, TNF alpha inhibitor, infliximab, adalimumab, golimumab and biological." (PMID 31126015, 2019). "We utilized gene set variation analysis and transcriptomic data from inflammatory bowel disease sufferers to stratify patients at baseline or after anti-TNF treatment in clinical responders and non-responders." (PMID 31039157, 2019). "The Pregnancy in Inflammatory Bowel Disease and Neonatal Outcomes (PIANO) registry intends to determine the adverse outcomes among pregnant women with IBD and their offsprings on AZA, 6MP and anti-TNF biologics." (PMID 31700750, 2019). "Biologic agents such as the TNF‐α inhibitor infliximab have had a substantial, positive impact on the treatment of many chronic immune‐mediated inflammatory disorders, including inflammatory bowel diseases (IBD), inflammatory rheumatic diseases and chronic plaque psoriasis." (PMID 30762274, 2019). "Since anti-tumor necrosis factor (TNF)-α agents (TNF-α inhibitors) induce both clinical response and remission in patients with moderate to severe inflammatory bowel disease (IBD), the use of anti-TNF therapies has fundamentally changed the approach to treatment for patients with IBD." (PMID 30286108, 2018). "Therefore, TNF-α targets were proposed as potential treatment options and today anti-TNF-α drugs are the gold standard in inflammatory bowel disease therapy." (PMID 30518097, 2018). "The aim of this study was to describe the surgical stress response in patients with inflammatory bowel disease (IBD) and to investigate whether the pre-operative administration of anti-tumor necrosis factor alpha (anti-TNF-α) agents modify the surgical stress response." (PMID 30390672, 2018). "The prospective interventional substudy proved that anti-TNF therapy has a favorable effect on insulin sensitivity in nondiabetic, nonobese patients with inflammatory bowel disease." (PMID 29576769, 2018).